MYC (MYC proto-oncogene, bHLH transcription factor)
Diseases named in the same sentence as MYC in open-access papers (continued):
Sharing a sentence is not in itself a finding about the gene and the disease.
cancer (continued). "Emerging evidence indicates that MYC upregulation is not limited to cancer cells but also extends to cancer-associated fibroblasts (CAFs)." (PMID 37755397, 2023). "Most PDACs harbor oncogenic KRAS mutations and elevated MYC signaling leading to dysregulation of global transcription and proliferation, potentially sensitizing cancer cells to therapeutic targeting with transcriptional inhibitors." (PMID 37831776, 2023). "These cancers have gained the classification of MYC-associated tumors, because this oncoprotein has been demonstrated to play a key role in the physiopathology of these diseases." (PMID 37457123, 2023). "Human c-Myc (MYC) is also one of the most frequently deregulated oncoproteins in many cancer types and a hallmark of the majority of human cancers." (PMID 37174665, 2023). "MYC is one of the most widely investigated cancer-causing genes, being implicated in the formation, maintenance and progression of several different cancer types." (PMID 37170221, 2023). "Greater skipping of this exon was also seen in MYC-active tumors in a pan-cancer analysis that implicated a network of SR proteins in its regulation." (PMID 37399401, 2023). "Proto-oncogenes (including MYC) and certain pathogenic stressors (e.g., hypoxia) directly drive this process, which is necessary for malignant transformation or cancer cell survival." (PMID 38002277, 2023). "This includes the Chromosome 8q24 region, all heavily associated with cancer (over 108 citations), with the MYC locus, as well as with several long non-coding RNAs loci—PCa Associated Transcript 1 (PCAT1) and PCAT2." (PMID 36765779, 2023). "Through functional enrichment analyses, we identified WDHD1 as a key participant in cell cycle regulation and DNA damage repair processes while also being closely associated with several pathways associated with cancer, including E2F, MYC, and mTOR signaling." (PMID 37759234, 2023). "Oncogenic kinases, in collaboration with MYC, can cause cancer cells to undergo metabolic reprogramming to actively sustain the increasing demand for the resources needed to increase cell mass and improve DNA replication and cell division." (PMID 38002277, 2023). "As such, MYC-related, well-known partner molecules associated with various cancers were also identified by this analysis (inset)." (PMID 37117191, 2023). "The parent G-quadruplex is a 27 nucleotide (nt) G4 formed in the nuclease hypersensitive element (NHE) region of the c-MYC promoter associated with different forms of cancer, and predominantly involved in the regulation of expression of the c-MYC gene." (PMID 36980918, 2023). "The c-MYC gene is part of a family composed of two other genes, MYCN and MYCL, that, like with c-MYC, encode for the proteins involved in cancer development." (PMID 36979947, 2023). "MYC is an oncoprotein causally involved in the majority of human cancers and a most wanted target for cancer treatment." (PMID 36765784, 2023). "Another transcription factor which constitutes a hallmark signature of the occurrence and development of cancer is MYC." (PMID 37239035, 2023). "This cellular delivery system has been successfully applied to transfer small peptides into cancer cells with elevated MYC oncoprotein levels leading to a loss of viability, growth suppression, and apoptosis." (PMID 36969025, 2023). "MYC levels are tightly regulated, and deregulation of MYC has been associated with numerous diseases including cancer." (PMID 37941901, 2023). "In contrast, the DAMPs in the nuclear DAMPs subtype triggered cancer hallmark MYC targets, NOTCH signaling, TGF-β signaling, unfolded protein response (UPR), MTORC1 signaling, and IL-8 production." (PMID 37033966, 2023). "Results indicated that some cancer hallmarks were much more enriched in the high-risk score group, such as MYC and MTOR-related pathways." (PMID 38022584, 2023).
cancer (continued). "As for CAFs, miR-105 can also activate MYC signaling in cancer-associated adipocytes to induce a metabolic program secreting energy-rich metabolites to fuel neighboring cancer cells." (PMID 37108371, 2023). "While upregulation of MYC has been extensively implicated in the context of cancer, downregulation of MYC is associated with increased health span and lifespan." (PMID 37908640, 2023). "For example, the MYC oncogene family is frequently deregulated in most human cancers and is associated with poor prognosis and unfavorable patient survival." (PMID 36918935, 2023). "This loss in MYC abundance was accompanied by a significant decrease in the cell number of all five cancer cell lines after 24 hours of IACS-010759 treatment." (PMID 37130865, 2023). "Over the past three decades, researchers have sought to unravel the complex mechanisms that underlie the cooperative effects of RAS and MYC in cancer, yet many aspects of this interaction remain shrouded in mystery." (PMID 37755397, 2023). "The MYC-induced oncogenic and epigenetic reprogramming leads to the acquisition of cancer stem-like cell-associated properties and the induction of intratumoral heterogeneity." (PMID 37898690, 2023). "The TWIST1 and MYC genes are well-known and important regulators of cancer-associated processes and remain objects of active research in the field of oncology." (PMID 37298233, 2023). "MYC is one of the most extensively studied oncogenes associated with the formation, maintenance, and progression of various cancer types." (PMID 38017538, 2023). "Each signature was built using the top 500 genes associated with MYC in that cancer type or cancer subtype." (PMID 37059746, 2023). "Conversely, inhibition or removal of MYC consistently causes growth arrest of cancer cells both in culture and in vivo." (PMID 37731815, 2023). "Although large-scale genomic studies have identified many somatically mutated genes in G3-MB tumors, candidate cancer genes that trigger MYC activation and amplification as well as their underlying regulatory circuitries remain poorly defined." (PMID 36765089, 2023). "Previous studies have revealed an association of high MYC expression with metabolic alterations in cancer cells, including aberrant protein glycosylation 24,25." (PMID 36632215, 2023). "Some of the genes encompassed by these CNAs are known cancer genes and have been previously associated with OS pathogenesis, such as MYC, RB1, and RECQL4." (PMID 37445641, 2023). "We next investigated the S03 state of fibroblasts in detail and found that three cancer hallmark-related pathways were significantly enriched by marker genes, including MYC targets, KRAS signaling down and cytokines." (PMID 37500893, 2023). "The present study aimed to investigate the role of activated STAT3 in promoting MB pathogenesis and chemoresistance via inducing the cancer hallmark MYC oncogene." (PMID 37190167, 2023). "MYC has been extensively investigated as a predominant cancer-causing gene and is associated with the cell cycle, differentiation, and apoptosis." (PMID 36672275, 2023). "Considering its myriad of functions, c-MYC is tightly regulated by developmental and mitogenic signals in normal cells, and dysregulation has been linked to oncogenic potential in several cancers." (PMID 37614497, 2023). "Metabolic rewiring in cancer is essential for malignant transformation or cancer cell survival and is directly driven by protooncogenes such as MYC activation and/or unique pathogenic stressors such as hypoxia." (PMID 37443779, 2023).
cancer (continued). "Here, we examined the binding of Dnmt3a-CD and M.SssI to the G4 structure formed by the purine-rich strand of the promoter region of the cancer-associated c-MYC gene (27fG4)." (PMID 38203216, 2023). "We also used the HALLMARK MYC targets to evaluate the MYC subnetworks in each of the normal tissues and cancer types, over half of which showed significant enrichment." (PMID 37142594, 2023). "MYC transformation also enhances expression of multiple RNA-binding regulators of splicing, leading to cancer-associated changes in alternative splicing programs." (PMID 37399401, 2023). "MYC is seldom mutated in cancer but rather upregulated via transcriptional induction due to chromosomal translocation or gene copy number amplification." (PMID 37731815, 2023). "We discover that MYC causally regulates glycosylation on the surface of cancer cells, which in turn facilitates immune evasion." (PMID 36897988, 2023). "The pluripotency markers NANOG and the Yamanaka factors OCT4, SOX2, KLF4 and c-MYC have previously been shown to be linked with enhanced cancer stem cell properties in cancer cells." (PMID 37950151, 2023). "The oncogene c-MYC is overexpressed in several cancer types, and it is a causative factor of at least 40% of malignancies." (PMID 37627164, 2023). "MYC plays a role in cell cycle progression, apoptosis, and cellular transformation, and mutations in this gene are frequently observed in numerous human cancers." (PMID 37346070, 2023). "On the other hand, JUND, a member of the AP-1 family that is related to MYC signaling pathway, regulates cell cycle and proliferation and its overexpression is linked to many types of cancers (PCA i.e.,)." (PMID 35741808, 2022). "In low‐risk CRC patients, cancer progression was found to depend upon oxidative phosphorylation and MYC and E2F targets." (PMID 35137551, 2022). "Several publications associate MYC with metastasis in breast and other cancers, sometimes as a repressor, but mostly as an inducer." (PMID 36860495, 2022). "Here we have reviewed the discovery of MTBP and the initial controversy with its function as well as its associations with proliferation, MYC, DNA replication, aging, and human cancer." (PMID 35741402, 2022). "MYC encodes transcription factors associated with cancer cell-cycle progression, proliferation, and biosynthesis." (PMID 36741696, 2022). "Recent work also implicated ADSL in the activation of MYC, which plays a major role in controlling metabolism and proliferation in cancer cells." (PMID 35133277, 2022). "MYC dysregulation occurs in most cancers and is often associated with aggressive disease, treatment resistance, and poor prognosis." (PMID 36313441, 2022). "Amplification of MYC oncogenes has been demonstrated to cause sensitivity to ferroptosis and iron addiction in other cancer types." (PMID 36698390, 2022). "Our investigations into a protein named MTBP revealed that it associates with MYC and helps its pro-growth and cancer promoting function." (PMID 35741402, 2022). "While somatic mutation of MYC occurs at relatively low frequency in cancer, several common MYC mutations have well-defined oncogenic functions." (PMID 36018850, 2022). "The overexpression of c-MYC is a known driver of cancer progression and is associated with tamoxifen resistance." (PMID 35267559, 2022). "Similar to its functions in cancer progression, MYC has also been tightly linked with cell cycle re-entry in the onset and development of AD and other CNS disorders." (PMID 35328644, 2022). "Considering that the MYC gene is an important proto-oncogene, MYC mutation or overexpression drives the growth of numerous cancers." (PMID 35369066, 2022). "We also describe the emerging role of the circPVT1/lncPVT1/c-MYC paradigmatic network in cancer disease detailing the molecular mechanisms underlying its pro-tumorigenic activities." (PMID 35090471, 2022).
cancer (continued). "The therapeutic potential of ML-792 (hence, targeting sumoylation) is particularly remarkable in cancers bearing MYC mutations or amplifications." (PMID 35269436, 2022). "These include pro-proliferative E2F, MYC, cell cycle, DNA repair, and inflammatory signatures, which were recently linked to more aggressive cancers." (PMID 36534167, 2022). "The MYC proto-oncogene encodes a transcription factor that is overexpressed in many human cancer types, and dysregulation of MYC signaling is implicated in the molecular and histologic heterogeneity of SCLC." (PMID 35941997, 2022). "Amplifications at these loci have been previously associated with aggressive and drug‐resistant cancers and included several oncogenes such as MYC, CCND1, and multiple fibroblast growth factors." (PMID 35671075, 2022). "MYC oncogene is involved in the majority of human cancers and is often associated with poor outcomes, rendering it an extraordinarily desirable target, but therapeutic targeting of c‐Myc protein has been a challenge for >30 years." (PMID 35048559, 2022). "The targets of MDs include three stem cell-related transcription factors frequently implicated in cancer: MYC, SOX2 and P63." (PMID 35325167, 2022). "Since MYC gene is often mutated and constitutively expressed in cancer cells, it can be used as a therapeutic target." (PMID 35328482, 2022). "Next to NF-κB, MYC transcription factors, including MYC, N-MYC, and L-MYC, are key players in cell growth and brain development and are implicated in most human cancers." (PMID 36361720, 2022). "We selected the MIR17-HG gene, which encodes an oncomir precursor, is a prominent target of MYC in cancer cells, and is activated by TRRAP in HCT116 cells." (PMID 35244540, 2022). "MAX gene-associated protein (MGA), a suppressor of MYC, is frequently subject to loss-of-function mutations and copy-number deletions in multiple cancer types." (PMID 35054466, 2022). "Previous articles showed that the rs6983267 SNP located in the MYC enhancer region is related to the susceptibility of various cancers." (PMID 35814404, 2022). "The proto-oncogene MYC has been implicated in the formation, maintenance, and progression of a number of different cancer types." (PMID 36299451, 2022). "The location of lncRNA PVT1 is thought to be a cancer risk locus shared with the well-known MYC oncogene." (PMID 36118202, 2022). "There was high similarity of the impact of collagen mutations on expression of cancer hallmarks highlighted by the higher expression of cell cycle drivers including E2F targets and MYC gene sets." (PMID 35120467, 2022). "The proto-oncogene MYC is important for development and cell growth, however, its abnormal regulation causes cancer." (PMID 35039581, 2022). "The metabolic rewiring of cancer cells is partly dependent on mutations in oncogenic driver genes, such as MYC and KRAS." (PMID 36612058, 2022). "The T58A mutant variants of MYC disrupt the proteasome signal, thus potentiating their effects, producing a robust cancer phenotype." (PMID 35729105, 2022). "Comparative integrative multi-omic analyses of these large datasets reveal cancer-selective MSI1-bound targets sharing multiple MYC associated pathways, providing a valuable resource for context-specific therapeutic targeting of G3 MB." (PMID 36473869, 2022). "The central premise of our finding relies on the observation that MYC is rewired from opposing PLA2G4F expression in early cancer to being positively associated with it in progressively advanced disease." (PMID 36181613, 2022).
cancer (continued). "Cancer-associated proteins, such as MYC, IGF-1, and MMP9 were identified as the main hubs in the resulting networks, and it had been previously reported that they were related to tumorigenesis and metastasis." (PMID 35711939, 2022). "This allowed them to show that several SE regions presenting copy number gains were associated with the overexpression of four neighboring cancer-associated genes, involving again the MYC oncogene." (PMID 35053311, 2022). "Previous studies have shown that the rs6983267 SNP located in the MYC enhancer region is related to the susceptibility of various cancers, including prostate cancer, colorectal adenoma and cancer, thyroid cancer, endometrial carcinoma, and ovarian cancer." (PMID 35814404, 2022). "Wang’s research highlights how depletion of MYC can inhibit the proliferation of normal human and cancer cells caused by MYC." (PMID 36057607, 2022). "This is best established in cellular models of MYC-driven cancers, where loss-of-function screens revealed a cancer-specific dependency on SUMOylation6,7." (PMID 35022408, 2022). "Keeping the homeostatic levels of MYC is vital for normal cell function; its overexpression is associated with several cancers." (PMID 35996406, 2022). "In the GSEA, AC116025.2 upregulation was associated with cell cycle activities and cancer-related pathways such as E2F targets, G2M checkpoint, MYC targets, MTORC1 signaling, and mitotic spindle (right)." (PMID 35572559, 2022). "In summary, lower c-MYC levels caused by the decreased expression of NM23-H2 in cancer cells would diminish apoptosis of cancer cells and enhance metastatic potential as well." (PMID 35625576, 2022). "In fact, PRMT5 expression is inversely correlated with FBXW7 and closely associated with aberrant MYC function in human cancers." (PMID 35346215, 2022). "PVT1, which is transcribed 52 kilobases downstream of MYC, is co‐amplified with MYC in many cancers and its increased expression is associated with a poor prognosis." (PMID 34668345, 2022). "One road to target cancers with oncogenic MYC activity is to exploit cellular vulnerabilities associated with the transcription factor." (PMID 35439169, 2022). "The analysis also predicted a major activation of transcription regulator, MYC, which is a classical oncogene in LUAD, and MYC expression has been shown to be associated with the stemness of cancer cells." (PMID 35433477, 2022). "Labile heme also causes the expression of oncogenes and cancer driver genes such as c-MYC, bcl-2, TGF-β, and Wnt by working on guanine quadruplex (G4) DNA structure as a heme-G4 DNA complex, resulting in a stimulation of cancer cell growth and proliferation." (PMID 36686754, 2022). "Fourth, among the “oncogenes”, high-level gene amplification, defined as >4.4 copies/cell, was seen only with MYC and tended to be associated with subgroups of certain cancers such as breast, ovary, liver and lung as previously reported." (PMID 35203395, 2022). "As a recently revisited hallmark of cancer development, MYC transcription factors regulate almost every aspect of cellular metabolism and are dysregulated in most types of cancers." (PMID 36672769, 2022). "BET inhibitors’ anti-cancer efficacy can occasionally be linked to their effects on MYC transcription." (PMID 36286044, 2022). "In WT mice, GEM responses are driven by metabolic regulators (primarily lipid metabolism), while in Rag1KO mice, CPA and GEM responses are driven by chemical drivers, and cancer associated drivers were inhibited (MYC, SOX4, MYB)." (PMID 35309309, 2022). "Our GSEA identified MYC and its downstream targets as the top hallmark of cancer pathway that distinguishes early-onset versus control transcriptomes." (PMID 36139061, 2022). "Upregulation of Pol III activity is a hallmark of cancer, and several studies have linked MYC to Pol III-transcribed genes, Pol III transcription factors, and increased Pol III activity." (PMID 36710885, 2022).